DIAPH2 (diaphanous related formin 2)
Description:
Could be involved in oogenesis. Involved in the regulation of endosome dynamics. Implicated in a novel signal transduction pathway, in which isoform 3 and CSK are sequentially activated by RHOD to regulate the motility of early endosomes through interactions with the actin cytoskeleton.
Synonyms: DRF2; DIA; POF; POF2; DIA2; POF2A
Tractability: PROTAC: ubiquitination databases record sites on it; its protein half-life has been measured.
Gene: Protein-coding gene on chromosome X (96,684,712 to 97,604,997, forward strand). Ensembl gene ENSG00000147202.
Subcellular location: Cytoplasm, cytosol (Isoform 3); Early endosome
Subcellular location (Human Protein Atlas): Endoplasmic reticulum; Vesicles; Nucleoli
Pathways (Reactome):
Signal Transduction: RHO GTPases Activate Formins; RHOD GTPase cycle; RHOF GTPase cycle
Gene Ontology:
Molecular function: signaling receptor binding; actin binding; small GTPase binding
Biological process: actin filament polymerization; female gamete generation; actin cytoskeleton organization
Cellular component: actin filament; cytosol; early endosome
Homologues: Orthologues: chimpanzee DIAPH2 (98% identical), macaque DIAPH2 (98% identical), dog DIAPH2 (92% identical), pig DIAPH2 (91% identical), rabbit DIAPH2 (88% identical), rat Diaph2 (86% identical), mouse Diaph2 (85% identical), tropical clawed frog diaph2 (72% identical), zebrafish diaph2 (70% identical), Drosophila melanogaster dia (37% identical), Caenorhabditis elegans daam-1 (20% identical), Drosophila melanogaster Frl (19% identical), and 3 more. Paralogues in human: DIAPH3 (57% identical), DIAPH1 (55% identical), DAAM1 (22% identical), DAAM2 (21% identical), FMNL2 (20% identical), INF2 (20% identical), FMNL3 (20% identical), FMNL1 (19% identical), FHOD3 (17% identical), FMN2 (16% identical), GRID2IP (16% identical), FHOD1 (15% identical), and 6 more.
Diseases named in the same sentence as DIAPH2 in open-access papers:
DIAPH2 is named in the same sentence as 37 diseases in open-access papers, as found by Europe PMC text mining. Sharing a sentence is not in itself a finding about the gene and the disease. The quoted sentences say what the papers report.
premature ovarian failure (13 papers, 2013 to 2025). "With limited information available, DIAPH2 is known to potentially play a role in oogenesis, and its variant may be associated with Premature Ovarian Failure 2A and amenorrhea." (PMID 40282394, 2025). "Notably, the X-linked gene, DIAPH2 (diaphanous related formin 2), known to be related with premature ovarian failure, has been suggested to be associated with AMD." (PMID 38421830, 2024). "DIAPH2 has been implicated in premature ovarian failure (POF2A, MIM: 300511), also known as primary ovarian insufficiency, which manifests as premature menopause." (PMID 34685534, 2021). "Primary ovarian failure (POF) has been associated with deletions of the FMR1 gene (POF1) at Xq26–q28 and the DIAPH2 gene (POF2A) at Xq21.33." (PMID 24778889, 2014). "Notably, FMR1, DIAPH2, POD1B, and BMP15 were previously designated as premature ovarian failure (POF) loci, namely, POF1, POF2A, POF2B, and POF4, respectively." (PMID 37033245, 2023). "In addition, three genes (DIAPH2, AFF2, POF1B) were involved in functions related to premature ovarian failure." (PMID 24422716, 2014).
ovarian failure (5 papers, 2020 to 2023). "Premature ovarian failure 2A (POF2A) was described to result from deletion or mutation in the DIAPH2 gene on chromosome Xq22 (OMIM# 300108)." (PMID 37202823, 2023).
laryngeal carcinoma (4 papers, 2021 to 2024). Carcinoma that arises from the laryngeal epithelium. "The research showed that polymorphism rs6620138 DIAPH2 gene was associated with the pathogenesis of laryngeal cancer." (PMID 34299935, 2021). "RESULTS: The results showed that rs6620138 DIAPH2 polymorphism could increase the onset risk of laryngeal cancer." (PMID 34299935, 2021). "Genetic susceptibility plays a role as well, with certain genetic polymorphisms, such as those in the DIAPH2, PTPRD, and HIC1 genes, being associated with an increased risk of laryngeal cancer." (PMID 38835555, 2024). "The aim of our study was to determine the relationship between genetic variations DIAPH2 (rs6620138), PTPRD (rs3765142) and HIC1 (rs9901806) and laryngeal cancer risk in 267 patients with histologically confirmed laryngeal cancer and 157 controls." (PMID 34299935, 2021). "Our results provide a basis to begin basic research on the role of DIAPH2 gene in the pathogenesis of laryngeal cancer." (PMID 34299935, 2021). "The relationship between the genetic variation of DIAPH2, PTPRD and HIC1 genes and the genetic susceptibility to laryngeal cancer was investigated in this study for the first time." (PMID 34299935, 2021). "In our observation of genetic risk of laryngeal cancer, we considered three genes: the DIAPH2 (diaphanous related formin 2) gene, the PTPRD (protein tyrosine phosphatase receptor Type D) gene and the HCI1 (hypermethylated-in-cancer 1) gene." (PMID 34299935, 2021). "The aim of our study was to try to find a link between the studied polymorphisms of the DIAPH2, HIC1 and PTPRD genes and the risk of laryngeal cancer development." (PMID 34299935, 2021). "Statistical analysis to calculate the relationship between DIAPH2, PTPRD and HIC1 genes polymorphism and pathogenesis of laryngeal cancer." (PMID 34299935, 2021). "We show a significant difference in the allele’s distribution of DIAPH2 and HIC1 between the study subgroup patients with laryngeal cancer and control subgroups." (PMID 34299935, 2021). "This study was designed to assess the association between DIAPH2, PTPRD and HIC1 SNPs and laryngeal cancer risk." (PMID 34299935, 2021). "We hypothesized that if we showed a difference in the distribution of the polymorphisms of the DIAPH2, HIC1 and PTPRD genes studied, this would indicate a significant effect of these genetic variations on the risk of developing laryngeal cancer." (PMID 34299935, 2021). "The relationship between genetic variations DIAPH2 (rs6620138), PTPRD (rs3765142) and HIC1 (rs9901806) and the onset of laryngeal cancer were investigated." (PMID 34299935, 2021).
colorectal cancer (3 papers, 2019 to 2024). A primary or metastatic malignant neoplasm that affects the colon or rectum. "The rs12851931 variant of the DIAPH2 gene was associated with a higher risk of cancer development (ovarian cancer or colorectal cancer) and could be related to LSCC, as indicated in our study." (PMID 38844723, 2024). "In colorectal cancer, DIAPH2 expression stimulates actin nucleation and microtubule stabilization, potentially controlling the cell cycle in a CDC42-independent manner." (PMID 33302475, 2020). "In this study, we analyzed the functional role of the formin Drosophila Homologue of Diaphanous2 (Diaph2) in colorectal cancer cells." (PMID 30926831, 2019). "This analysis revealed that depletion of Diaph2 reduced the number of cells with aligned chromosomes by 20% (k.d.1) and 30% (k.d.4), indicating that Diaph2 is indeed involved in the control of chromosome alignment in colorectal carcinoma cells." (PMID 30926831, 2019). "In this study, we addressed the functional role of human Diaph2 for progression of colorectal carcinoma cells and its potential function in chromosome alignment, metaphase progression and MT-modification." (PMID 30926831, 2019).
breast carcinoma (2 papers, 2015 to 2018). "The miRNA let-7b-5p was also shown to have a tumor suppressor role in breast cancer patients with lymph node metastasis, by repressing the expressions of the genes PAK1, DIAPH2, RDX and ITGB8." (PMID 26763900, 2015).
Hearing impairment (2 papers, 2021 to 2023). A decreased magnitude of the sensory perception of sound. "Here, we investigate the role of the third member of the family, DIAPH2, in nonsyndromic hearing loss, prompted by the identification, by exome sequencing, of a predicted pathogenic missense variant in DIAPH2." (PMID 36689403, 2023). "We propose that a hemizygous missense variant in DIAPH2 (p.I290V) on the X-chromosome may underlie the progressive hearing impairment in a family of Italian origin, possibly impairing RhoA-dependent activation of DIAPH2." (PMID 36689403, 2023).
laryngeal squamous cell carcinoma (2 papers, 2021 to 2024). A squamous cell carcinoma that arises from the larynx. "The DIAPH2 gene is one of the genes commonly associated with laryngeal squamous cell carcinoma (LSCC)." (PMID 38844723, 2024). "High expression of diaphanous related formin 2 (DIAPH2) was associated with poor overall survival in head and neck squamous cell carcinoma and laryngeal squamous cell carcinoma (LSCC)." (PMID 34299935, 2021).
lymph node metastasis (2 papers, 2015 to 2024). "High expression of DIAPH2 was associated with advanced tumor stage, lymph node metastasis and poor overall survival in LSCC patients." (PMID 38844723, 2024).
anaplastic astrocytoma (1 paper, 2021). "In detail, one patient collected tumor specimens in all stages of MT in the present cohort.PRKCQ,PPIF,NRP1,MEFV,GGT1,FAN1, andBTKmutations were found in both DA and anaplastic astrocytoma, whereas mutations ofTBC1D19,ESRRA,DIAPH2,COG6, andCBWD3occurred in HGA." (PMID 34430964, 2021).
ciliopathies (1 paper, 2021). "Given the similarity between DIAPHs 1, 2, and 3, and since mutations of DIAPH2 and DIAPH3 in humans give phenotypes commonly seen in ciliopathies, we reasoned that DIAPH2 and DIAPH3 proteins may also play roles in ciliogenesis and cilia maintenance." (PMID 33872598, 2021).
colon cancer (1 paper, 2019). "Based on these data, we examined if also in colon cancer cells Diaph2 is essential for proper chromosome alignment and spindle MT-dynamics." (PMID 30926831, 2019). "In this study, we analyzed the functional role of Diaph2 in the control of spindle MT-dynamics of colon cancer HT29 cells." (PMID 30926831, 2019).
deafness (1 paper, 2023). An inherited or acquired condition characterized by the complete loss of the ability to hear from one or both ears. "Despite the efforts to find a second NSHL family with potentially pathogenic variants in DIAPH2, we still lack additional genetic data confirming the association of this gene with deafness." (PMID 36689403, 2023). "Although the lack of hearing phenotype in mutant mice does not help in supporting our hypothesis of a causal relationship between Diaph2 and deafness, there are few examples of genes causing hearing loss in humans that do not cause the same phenotype in mice." (PMID 36689403, 2023). "Additional molecular studies will also be needed to better clarify the role of DIAPH2 in normal hearing and deafness." (PMID 36689403, 2023). "Our findings indicate that DIAPH2 may play a role in the inner ear; further studies are however needed to clarify the contribution of DIAPH2 to deafness." (PMID 36689403, 2023).
hepatocellular carcinoma (1 paper, 2020). A malignant tumor that arises from hepatocytes. "While only limited information on DIAPH2 is available, DIAPH3, a closely related family member with 57% sequence homology and several common protein binding domains, does promote cell growth and metastasis in hepatocellular carcinoma." (PMID 32276641, 2020).
melanoma (1 paper, 2017). A malignant, usually aggressive tumor composed of atypical, neoplastic melanocytes. "This indicates that RhoD can regulate the formation of stress fibers and adhesion plaque through DIAPH2, and influence the migration and invasion of melanoma cells." (PMID 28404912, 2017).
prostate tumors (1 paper, 2016). "However, MIC(X1; X2; Y) suggests that LINC01278, RGS9 and DIAPH2 are important informative genes for prostate tumors, and should be given proper attention." (PMID 27470995, 2016).
Sepsis (1 paper, 2022). Sepsis is defined as life-threatening organ dysfunction caused by a dysregulated host response to infection. "Any of the three and/or the pooled sepsis groups significantly differed from the ICU controls for a total of eleven genes, including higher sepsis levels for the endo-lysosomal genes DIAPH2, GUSB, HEXA, LAIR1, and SGSH." (PMID 35844509, 2022).
cancer (8 papers, 2016 to 2024). A tumor composed of atypical neoplastic, often pleomorphic cells that invade other tissues. "We also found that phenanthriplatin, but not cisplatin, downregulates two genes, AGAP1 (ArfGAP with GTPase domain, ankyrin repeat and PH domain 1) and DIAPH2 (diaphanous related formin 2), involved in cancer cell cytoskeletal remodeling." (PMID 33302475, 2020). "The key cancer-related genes affected by HPV integrants are Diaphanous-related formin 2 (DIAPH2) gene rearrangements and Tumour protein 63 (TP63) gene promoter aberration and Proviral integration site for Moloney murine leukaemia virus 1 (PIM1) and Forkhead box E1 (FOXE1) gene amplification." (PMID 38643337, 2024). "However, phenanthriplatin may also act to prevent cancer cell cytoskeletal stability by downregulating DIAPH2, while cisplatin regulation of cancer cell microtubule stability may act instead through microRNA and CDC42 signaling to modulate A549 cancer cell proliferation." (PMID 33302475, 2020). "Treatment of non-small cell lung cancer cells with phenanthriplatin, but not with cisplatin, downregulates DIAPH2 expression, with this effect being potentially useful for treating this type of cancer." (PMID 34685534, 2021).
tumor (6 papers, 2015 to 2024). "Heterozygotes of rs12851931 variant of the DIAPH2 gene were more often associated with T2 stage, while homozygotes were more likely to have higher tumor stages." (PMID 38844723, 2024). "Mammals possess three members of this protein family, diaphanous homolog 1 (DIAPH1), DIAPH2, and DIAPH3, which have been implicated in both normal cell physiology and tumor progression." (PMID 36589226, 2022). "The IHC data demonstrated that DIAPH1 and DIAPH3 expression were higher in tumor tissue when compared to adjacent normal tissue, and DIAPH2 was positively expressed in pancreatic acinar cells in adjacent normal tissue but not pancreatic ductal cells." (PMID 36589226, 2022). "The expression levels of DIAPH1, DIAPH2, and DIAPH3 in PAAD tumor tissues were significantly higher than in normal tissues in the consensus databases of TCGA and GTEx." (PMID 36589226, 2022). "Previous experimental studies suggested the role of miR-let-7b in suppressing tumors, which works by inhibiting tumor proliferation, invasion, and adhesion via interacting with various genes named HMGA2, RDX, DIAPH2, Ras c-myc, and PKA133." (PMID 35831411, 2022). "Notably, the expression levels of DIAPH1, DIAPH2, and DIAPH3 were significantly higher in PAAD tumor tissues than in normal tissues." (PMID 36589226, 2022). "As a tumor suppressor or tumor promoter, miR-let-7b has been found to halt cell proliferation, adhesion, and invasion by targeting Protein Code Gene (PKA1), Diaphanous Related Formin 2 (DIAPH2), Radixin (RDX), RAS, MYC, and High Mobility Group A2 (HMGA2) genes and their respective proteins." (PMID 34122072, 2021).
infection (1 paper, 2023). The state of being infected such as from the introduction of a foreign agent such as serum, vaccine, antigenic substance or organism. "The knockdown of DIAPH1 or DIAPH2 strongly reduced HIV-1 entry, an effect mimicked by SMIFH2, HIV-1-induced MT stabilization, and HIV-1 reverse transcription during early stages of infection." (PMID 37240404, 2023). "Conversely, the infection of non-human retroviruses such as Simian Immunodeficiency Virus and Murine Leukemia Virus was independent of them and did not result in MT stabilization, showing the functional specificity of DIAPH1 or DIAPH2 in HIV-1 infection." (PMID 37240404, 2023).
DIAPH2 also shares sentences with these, for which no sentence is quoted: Infertility (2 papers); Premature ovarian insufficiency (2); amenorrhea (1); autism spectrum disorder (1); bacterial infections (1); cardiomyopathy (1); cortical blindness (1); head and neck squamous cell carcinoma (1); Intellectual disability (1); microcephaly (1); Obesity (1); oculocerebrorenal syndrome of Lowe (1); ovarian carcinoma (1); peripheral neuropathy (1); renal disease (1); systemic sclerosis (1); Thrombocytopenia (1); viral infections (1).